PCSK9 (proprotein convertase subtilisin/kexin type 9)
Diseases named in the same sentence as PCSK9 in open-access papers (continued):
Sharing a sentence is not in itself a finding about the gene and the disease.
dyslipidemia (continued). "The major significance and take home message of this work is the development of a novel and promising approach for human therapeutic intervention of the PCSK9 pathway and hence for reducing some of the cardiovascular risk factors associated with the metabolic syndrome." (PMID 20498851, 2010). "In this narrative review, we focus on current strategies targeting PCSK9 and critically discuss some uncertainties regarding the allocation strategy, paying particular attention on the role of inclisiran in the treatment of dyslipidemia in high-/very high-risk subjects." (PMID 36087240, 2022). "In the 2019 ESC/EAS Guidelines for the management of dyslipidemias, it is stated that for secondary prevention, patients at very high risk not achieving their goal on a maximum tolerated dose of statin and ezetimibe, a combination with a PCSK9 inhibitor is recommended." (PMID 34887772, 2021). "Similarly, clinical, genetic, and experimental evidence linked PCSK9 with metabolic syndrome." (PMID 31672148, 2019). "There is evidence for resistance to some drugs for the treatment of dyslipidemia, such as PCSK9 inhibitors." (PMID 42165959, 2026). "In conclusion, the study demonstrates the real-world efficacy of PCSK9-mAb therapy in achieving sustained LDL-C reduction and reducing cardiovascular hospitalization rates, highlighting its role in managing high-risk dyslipidemia patients." (PMID 40760109, 2026). "This diversity in baseline LDL-C levels of the patient cohorts ranges from ≥70 mg/dL to >200 mg/dL and points to the fact that the benefits of PCSK9 inhibitors are observed in different severities of dyslipidemia." (PMID 40110272, 2025). "Based on TriNetX database, individuals T2D and dyslipidemia who were newly prescribed either a PCSK9 inhibitor or a statin between January 1, 2015, and April 30, 2025, were identified." (PMID 41347133, 2025). "Statins remain the cornerstone of dyslipidemia management in T1D, with emerging evidence supporting ezetimibe and PCSK9 inhibitors." (PMID 40943477, 2025). "Evolocumab improves myocardial remodelling and cardiac function in metabolic syndrome models by suppressing PCSK9-mediated activation of the NLRP3 inflammasome and its downstream Caspase-1/IL-1β axis." (PMID 41008547, 2025). "These pleiotropic mechanisms position PCSK9 at the intersection of dyslipidemia, inflammation, and thrombosis—key drivers of ischemic stroke, which remains a leading cause of mortality and long‐term disability worldwide." (PMID 41190281, 2025). "Proprotein convertase subtilisin/kexin type 9 (PCSK9) inhibitors are a new class of drugs used for the treatment of dyslipidemia." (PMID 40779566, 2025). "Pharmacological treatment options include statins as a first-line therapy, with ezetimibe and Proprotein Convertase Subtilisin/Kexin Type 9 (PCSK9) inhibitors as add-on therapy options in case of persistent dyslipidemia." (PMID 41299307, 2025). "These proatherogenic and immunomodulatory effects position PCSK9 as a potential mechanistic link between dyslipidemia, vascular inflammation, and kidney damage." (PMID 40868936, 2025). "Recent research has established a link between low levels of PCSK9 and condition such as metabolic syndrome, obesity, insulin resistance and diabetes." (PMID 40133913, 2025). "In every other case report, a change in dyslipidemia treatment was made, with PCSK9 inhibitors considered the best option." (PMID 40249406, 2025). "In CKD, PCSK9 has gained interest not only because of its effect on dyslipidemia but also due to its involvement in inflammation." (PMID 40868936, 2025).
dyslipidemia (continued). "Additional clinical studies have demonstrated elevated PCSK9 levels in patients with type 2 diabetes and metabolic syndrome, even after adjustment for LDL-C levels." (PMID 41516208, 2025). "Many current lipid-lowering drugs upregulate LDL-R by stimulating SREBP-2, leading to PCSK9-mediated drug resistance in dyslipidemia, which can be regarded as a useful adjunct to statin therapy." (PMID 38957396, 2024). "There is accumulated evidence in support of the fact that PCSK9 can beconsidered a promising potential therapeutic target for dyslipidemia and CVDs." (PMID 39228490, 2024). "When disparities in drug utilization were identified across regions, it was anticipated that PCSK9 inhibitors would be utilized more frequently in regions with a higher number of dyslipidemia patients." (PMID 38840134, 2024). "In the present study, we confirm the relationship between the PCSK9 concentration and the degree of metabolic control in patients with T1D and also with components of metabolic syndrome." (PMID 38532033, 2024). "The present study shows that dyslipidemia induced by either HFD or PCSK9-GOF elicits renal fat deposition, dysfunction, and fibrosis." (PMID 39094771, 2024). "The two human monoclonal antibodies (mAbs) against PCSK9 currently available, evolocumab and alirocumab, have a central role in dyslipidemia management, especially after the ambitious LDL-C goals outlined in the last guidelines." (PMID 38592091, 2024). "The improvement of RNA therapeutics also involved the field of dyslipidemia, providing approaches to regulating the expression of atherogenesis key players, just like PCSK9." (PMID 38592091, 2024). "The PCSK9 concentration was 0.37 ± 0.12 mg/L, which was greater in patients with worse glycemic control (HbA1c > 7.5%), dyslipidemia and high EAT volume (iEAT > 75th percentile)." (PMID 38532033, 2024). "A key finding from a European GWAS of lipid levels is the discovery of a causal PCSK9 loss-of-function (LoF) variant (p.Arg46Leu; rs11591147), which has led to the development of PCSK9-inhibitors to treat dyslipidemia." (PMID 37903942, 2024). "As research progresses, PCSK9 inhibitors are anticipated to play a crucial role in the comprehensive management of dyslipidemia, aiding in both its prevention and the mitigation of its consequences." (PMID 39650150, 2024). "Several studies haveinvestigated the applicability of genome editing for managing dyslipidemia viatargeting PCSK9 and here we discuss some of these investigations." (PMID 39228490, 2024). "Because a small number of hepatic LDL receptors lead to elevated plasma LDL levels, the development of drugs that can increase available LDL receptors such as the PCSK9 inhibitor is one of the strategies for dyslipidemia treatment." (PMID 39598338, 2024). "The emergence of proprotein convertase subtilisin/kexin type 9 inhibitors offered dyslipidemia patients an alternative to statins for lipid‐lowering treatment." (PMID 38590082, 2024). "The combination of statins and PCSK9 inhibitors represents a highly effective approach for managing dyslipidemia and reducing CV risks." (PMID 39539858, 2024). "Further research has explored the relationship between serum PCSK9 levels and various aspects of psoriasis, including disease severity, inflammation, metabolic syndrome, and the effects of systemic therapies." (PMID 38185721, 2024). "Proprotein convertase subtilisin/kexin type 9 (PCSK9) inhibitors are an important breakthrough in treating dyslipidemia since they lessen the degradation of LDL receptors, allowing for significant drops in LDL-C levels." (PMID 39176329, 2024). "The PCSK9 concentration was significantly greater in T1D patients with a high WC, TG ≥ 1.7 mmol/L, dyslipidemia, HbA1c > 7.5% (58 mmol/mol), or an iEAT above the 75th percentile." (PMID 38532033, 2024).
dyslipidemia (continued). "Statin, an HMGCR inhibitor, is a cornerstone for treating dyslipidemia, and other lipid-lowering drugs include ezetimibe, proprotein convertase subtilisin/kexin type 9 (PCSK9) inhibitors, and bile acid sequestrants." (PMID 39598338, 2024). "The Food and Drug Administration (FDA) endorses new agents to address dyslipidemia such as proprotein convertase subtilisin/kexin type 9 inhibitors (PCSK9-i) and Inclisiran, a small interfering RNA." (PMID 39618878, 2024). "In the prospective, observational GOULD (Getting to an Improved Understanding of Low‐Density Lipoprotein‐Cholesterol and Dyslipidemia Management) study, 92% of patients continued to receive PCSK9 inhibitors after 2 years." (PMID 39470058, 2024). "Due to the significant incidence of dyslipidemia, PCSK9 inhibition has also emerged as a prominent focus of translational medicine research." (PMID 38397888, 2024). "It was discovered that PCSK9 inhibitors are a dependable, secure, and effective treatment of dyslipidemia in CKD patients to lower LDL-C levels." (PMID 39176329, 2024). "Historically, the discovery of PCSK9 as a key regulator of LDL-C clearance opened new avenues for addressing dyslipidemia and cardiovascular disease (CVD)." (PMID 39650150, 2024). "Over recent years, PCSK9 has emerged as a key target of drug development for mitigating dyslipidemia." (PMID 38770531, 2024). "Statins and PCSK9 inhibitors show promise in managing dyslipidemia and reducing cardiovascular events in PLWH." (PMID 39311207, 2024). "Therefore, the study hypothesizes that mutations of lipid-related EHBP1 SNPs may result in different lipid phenotypes and these SNPs might interact with the environment to alter dyslipidemia risk; moreover, they might interact with PCSK9 to affect lipid levels." (PMID 39731114, 2024). "PCSK9 inhibitors have been produced and recommended in the guidelines for the management of dyslipidemia." (PMID 37888673, 2023). "Although the lipid-lowering efficacy of PCSK9 inhibitors is supported by a wealth of evidence in dyslipidemia, the use of PCSK9 inhibitors remains low in the Arabian Gulf for patients with FH and those with highly elevated LDL-C levels." (PMID 36662739, 2023). "New drugs for managing dyslipidemia have recently emerged, such as proprotein convertase subtilisin/kexin type 9 (PCSK9) inhibitors." (PMID 37256879, 2023). "The study population consisted of 39 patients with dyslipidemia who were eligible for PCSK9 inhibition therapy." (PMID 36768645, 2023). "The possible mechanism of action of amla in regulating dyslipidemia is via PCSK9-inhibition, PPAR-α agonism, as well as its strong antioxidant effects." (PMID 38089061, 2023). "Currently, dyslipidemia drugs represent a substantial part of clinical cardiovascular research, with the emerging PCSK9 antibodies and antisense oligonucleotides further boosting research in this area." (PMID 37790806, 2023). "As a result, decreasing plasma levels of PCSK9 presents itself as an intriguing possible treatment target for dyslipidemia in diabetic patients." (PMID 36936164, 2023). "Inclisiran is a novel lipid-lowering drug that interferes with the PCSK9-dependent hypolipidemic pathway, and it can play a major role in the therapy of dyslipidemia in the future." (PMID 37047830, 2023). "In this review, the evidence of lipid-lowering medications such as statin, ezetimibe, and PCSK9 inhibitors for secondary stroke prevention and management of dyslipidemia for each subtype of stroke is described." (PMID 37109734, 2023). "In this review, we examined the evidence supporting lipid-lowering medications like statins, ezetimibe, and PCSK9 inhibitors for secondary stroke prevention and dyslipidemia management in different stroke subtypes." (PMID 37109734, 2023). "Specifically, PCSK9 levels were found to be higher in individuals with metabolic syndrome, insulin resistance, and elevated fasting glucose levels." (PMID 38028979, 2023).
dyslipidemia (continued). "Currently, PCSK9 inhibitors are an effective treatment options for patients with type 2 diabetes and mixed dyslipidemia." (PMID 38115042, 2023). "There is evidence for resistance to some drugs for the treatment of dyslipidemia, such as anti-PCSK9." (PMID 38003001, 2023). "The Food and Drug Administration has approved Proprotein Convertase Subtilisin/Kexin Type 9 (PCSK9) inhibitors for the treatment of dyslipidemia." (PMID 35706032, 2022). "Taken together, these studies strongly support PCSK9 blockage to improve hepatic steatosis in patients with severe dyslipidemia." (PMID 35162992, 2022). "Proprotein convertase subtilisin/kexin type 9 (PCSK9) inhibitors have been increasingly used in the management of dyslipidemia in individuals with T2DM." (PMID 36072863, 2022). "Coupled with a significant increase in PCSK9 levels in the peripheral blood after induction therapy, this confirms studies that have examined the development of metabolic syndromes, including dyslipidemia and cardiovascular diseases in ALL survivors." (PMID 36109804, 2022). "Our study aims to estimate the prevalence of dyslipidemia and high Lp(a) in the Lebanese population and to study the relationship of these variables with gender, age, body mass index (BMI), and PCSK9." (PMID 35893257, 2022). "Several studies found higher circulating PCSK9 levels in adult patients with metabolic syndrome, T2DM, and obesity." (PMID 36009507, 2022). "Statins, fibrates, cholesterol absorption inhibitors, niacin, bile acid sequestrants, proprotein convertase subtilisin/kexin type-9 (PCSK-9) inhibitors are the available therapeutic options to treat dyslipidemia." (PMID 35776741, 2022). "Further studies are clearly needed to validate if PCSK9 inhibition or LDL-R downregulation can ameliorate dyslipidemia in HBV-infected patients." (PMID 35162992, 2022). "The newly developed monoclonal antibody for PCSK9 allows patients with dyslipidemia to attain LDL-C levels as low as 0.78 mmol/L." (PMID 36291690, 2022). "This review aims at describing the role of the PCSK9 pathway in atherogenic dyslipidemia in transplant recipients, comparing the effectiveness of PCSK9i use in both the general population and in transplant patients." (PMID 35683632, 2022). "Statins are the first-line medications for dyslipidemia, and other options include fibrates, ezetimibe, and PCSK9 inhibitors." (PMID 35844338, 2022). "Circulating PCSK9 levels were associated with dyslipidemia, pathoglycemia, and the risk of incident GDM, indicating a potential link between PCSK9 and GDM." (PMID 35498417, 2022). "Various studies have found increased plasma PCSK9 levels in patients suffering from type 2 diabetes mellitus, metabolic syndrome or obesity." (PMID 33643060, 2021). "On the other hand, knockout of PCSK9 was found to ameliorate dyslipidemia after treatment with nephrotoxic serum." (PMID 34442464, 2021). "Subsequent studies focused on the effects of PCSK9 inhibition on biomarkers of atherosclerotic plaque destabilization release in hypertensive patients with dyslipidemia." (PMID 33808697, 2021). "The studies aimed to assess the effect of PCSK9 inhibitors on the serum levels of vulnerable plaque markers in patients with dyslipidemia." (PMID 33808697, 2021). "The identification of proprotein convertase subtilisin/kexin type 9 (PCSK9) inhibitors revolutionized the therapeutic management of dyslipidemia." (PMID 34067469, 2021). "Recent rat-based studies have also shown that proteinuria can induce hypersulfated hepatic heparan sulfate side chains of heparan sulfate proteoglycan, increasing the affinity to PCSK9 in sinusoids, and thus worsening dyslipidemia." (PMID 34822418, 2021).
dyslipidemia (continued). "The most striking finding in the present study was the positive relationship between circulating PCSK9 levels and incidence of high triglycerides, hypertension, type 2 diabetes, and metabolic syndrome only in female subjects." (PMID 34041285, 2021). "All 9 study patients were diagnosed with dyslipidemia and were prescribed lipid lowering medications other than PCSK9 monoclonal antibody." (PMID 33632254, 2021). "The effect of PCSK9 inhibition on postprandial lipid metabolism has been recently reported in type 2 diabetic patients with dyslipidemia." (PMID 33643062, 2021). "Consistently, in subjects with at least one of the metabolic syndrome risk factors, a diet supplemented with canola oil enriched with DHA (by 6%) lowered circulating PCSK9 and TG levels compared to canola and canola oleic diets." (PMID 32429343, 2020). "In patients with stable CAD, low plasma levels of PCSK9 were linked with a particular metabolic phenotype (low HDL-C, the metabolic syndrome, obesity, insulin resistance and DM)." (PMID 33023603, 2020). "In 2019, research showed that patients with stable coronary artery disease low PCSK9 plasma levels were associated with a particular metabolic phenotype (low HDL cholesterol, the metabolic syndrome, obesity, insulin resistance, and diabetes)." (PMID 32456228, 2020). "Pcsk9, which was a member of the subtilisin protease family, had been reported as a new target in dyslipidemia treatment." (PMID 32148538, 2020). "Over the recent decade, PCSK9 became the subject of numerous studies focused on understanding the role of PCSK9 in diseases other than dyslipidemia." (PMID 32456228, 2020). "Elevated PCSK9 is also observed in metabolic syndrome, which affects more than 50% of psoriatic patients." (PMID 32225075, 2020). "A recent study in patients with stable CAD demonstrated that low PCSK9 plasma levels are associated with low HDL-C, metabolic syndrome, obesity, insulin resistance, and diabetes, and diffuse non-obstructive coronary atherosclerosis." (PMID 32035487, 2020). "This warrants the study of the utility of these self-reported methods of compliance to optimize treatment with other dyslipidemia drugs such as ezetimibe and proprotein convertase subtilisin/kexin type 9 (PCSK-9) inhibitors." (PMID 32042518, 2020). "A previous clinical study has demonstrated that post‐menopausal women with metabolic syndrome had significantly increased PCSK9 level when compared with pre‐menopausal women with metabolic syndrome." (PMID 32628813, 2020). "Statins are established as first-line LLT in ACS patients but novel agents for managing dyslipidemia are now available, such as proprotein convertase subtilisin-kexin type 9 (PCSK9) inhibitors." (PMID 32660429, 2020). "Recently there has been more research performed to comprehend the role of PCSK9 in other diseases besides dyslipidemia." (PMID 32225075, 2020). "In patients with stable CAD, low PCSK9 plasma levels are associated with a particular metabolic phenotype (low HDL cholesterol, the metabolic syndrome, obesity, insulin resistance and diabetes) and diffuse non-obstructive coronary atherosclerosis." (PMID 31672148, 2019). "We found a relationship of low PCSK9 levels with insulin resistance or diabetes, obesity or metabolic syndrome." (PMID 31672148, 2019). "Because albumin is the most abundant serum protein produced by the liver, we reasoned that linking the expression of human PCSK9 to this promoter would induce a dyslipidemia similar to that observed in humans carrying PCSK9 gain-of function mutations." (PMID 30646909, 2019). "In the overall population, PCSK9 levels were significantly lower in patients with the metabolic syndrome, or diabetes, or high BMI, or low HDL cholesterol." (PMID 31672148, 2019).